CDC50CP (CDC50 family member C, pseudogene)
Synonyms: CDC50C; formerly TMEM30C; TMEM30CP
Gene: Transcribed unitary pseudogene on chromosome 3 (100,185,687 to 100,211,766, forward strand). Ensembl gene ENSG00000235156.
Subcellular location: Membrane